APOA1 (apolipoprotein A1)
Diseases named in the same sentence as APOA1 in open-access papers (continued):
Sharing a sentence is not in itself a finding about the gene and the disease.
idiopathic pulmonary fibrosis (11 papers, 2011 to 2025). Idiopathic pulmonary fibrosis (IPF) is a nonneoplastic pulmonary disease that is characterized by the formation of scar tissue within the lungs in the absence of any known cause. "This kind of activity, by affecting Smad proteins, was proven, e.g., for apolipoprotein A1, plant-derived hesperidin, paeoniflorin, and celasterol, as well as for two drugs approved in the treatment of idiopathic pulmonary fibrosis, nintedanib and pirfenidone." (PMID 35455420, 2022). "The present study, which investigated the therapeutic impact of ApoA1 on silica-induced experimental lung fibrosis, shows that overexpression of ApoA1 diminished the development of lung fibrosis and promoted the resolution of established fibrosis." (PMID 23409054, 2013). "Accumulation of foamy cells in smokers – a strong comorbidity factor in lung infections – reflects impaired lipid cellular metabolism, as reduced levels of apolipoprotein A1 (ApoA1) are found in the bronchoalveolar lavage fluid of patients with idiopathic pulmonary fibrosis (IPF)." (PMID 31134013, 2019). "Recently, we reported that ApoA1 is expressed in the lung epithelium, that lung ApoA1 levels were reduced in patients with idiopathic pulmonary fibrosis, and intranasal treatment with ApoA1 significantly attenuated experimental bleomycin-induced lung injury and fibrosis." (PMID 23409054, 2013). "ApoA1 appears to be a promising therapeutic agent for the treatment of established lung fibrosis." (PMID 23409054, 2013). "The restoration of lipoxin A4 may contribute to the protective effect of ApoA1 overexpression against silica-induced lung fibrosis." (PMID 23409054, 2013). "However, it is unclear whether ApoA1 administration after an injury can reduce established pulmonary fibrosis." (PMID 23409054, 2013). "In lung fibrosis, APOA1 has been demonstrated to inhibit the EMT process, which suggests that a low level of APOA1 may stimulate EMT and promote the differentiation of CTB-EVT, thereby maintaining the invasion capacity of placental villi in the third trimester." (PMID 40778280, 2025).
Parkinson disease (11 papers, 2013 to 2026). A progressive degenerative disorder of the central nervous system characterized by loss of dopamine producing neurons in the substantia nigra and the presence of Lewy bodies in the substantia nigra and locus coeruleus. "A very recent study has identified low levels of plasma ApoA1 as a significant risk factor for Parkinson disease, and concentrations correlated with increased putaminal loss on DAT scan [32▪▪]." (PMID 23823465, 2013). "ApoA1 is a major component of high-density lipoprotein (HDL), and it is of note that statin use, which increases HDL, is associated with a reduced risk for Parkinson disease." (PMID 23823465, 2013).
atrial fibrillation (10 papers, 2014 to 2025). A disorder characterized by an electrocardiographic finding of a supraventricular arrhythmia characterized by the replacement of consistent P waves by rapid oscillations or fibrillatory waves that vary in size, shape and timing and are accompanied by an irregular ventricular response. "In addition, studies showed that the patients with atrial fibrillation had significantly lower ApoA1 levels than the control group." (PMID 38914982, 2024). "Also, the genetically predicted the ApoB/ApoA1 ratio had a significant positive association with the occurrence rates of PAD, non-rheumatic valve diseases, atrial fibrillation and atrial flutter (PFDR<0.05 in at least three MR methods in the four methods)." (PMID 38310324, 2024). "The relationship between serum apolipoprotein A1 (APOA1) and atrial fibrillation (AF) is not known." (PMID 37221493, 2023).
diabetic retinopathy (10 papers, 2014 to 2024). "The ApoA-1 levels were lower in patients with DM than in controls and were associated with diabetic retinopathy severity." (PMID 36619946, 2022). "Investigations of other ocular conditions (e.g., diabetic retinopathy, age-related maculopathy) have posited that increased APOA1 levels may indicate underlying inflammatory processes." (PMID 34602085, 2021). "Apolipoprotein A1 levels are reported to be inversely associated with diabetic retinopathy." (PMID 27795741, 2016). "On the other hand, serum levels of ApoB, ApoC3 and the ApoA1 to ApoB ratio showed positive correlations with diabetic retinopathy." (PMID 35628887, 2022). "An inverse correlation was found between the ApoA1 levels and the progression of diabetic retinopathy." (PMID 35628887, 2022). "By contrast, the serum levels of ApoB, ApoC3, and the ratio of ApoA1 to ApoB had positive correlations with diabetic retinopathy." (PMID 33213461, 2020). "Therefore, compared with high-density lipoprotein and lipid indicators, apolipoprotein A1 may be a more accurate and reliable biomarker of diabetes retinopathy (DR)." (PMID 39033211, 2024). "Both APOA1 and APOA2 are discussed as biomarkers and treatment targets in diabetic retinopathy (DR), polypoidal choroidal vasculopathy (PCV), and AMD, although there is no consistency in studies regarding the mechanism of action." (PMID 38792644, 2024). "In addition we found ALDH1A1, RBP4, APOB, APOA1, RBP1, APOE and RHO genes enriched in retinoid metabolic process as unique GO in diabetic retinopathy." (PMID 28761062, 2017).
lipid metabolism disorder (10 papers, 2014 to 2025). "In conclusion, the APOA1/C3/A4/A5 cluster holds potential as a novel target for addressing lipid metabolism disorders." (PMID 38927431, 2024). "Intensive research into the epigenetic regulatory patterns of the APOA1/C3/A4/A5 cluster will help increase our understanding of the pathogenesis of lipid metabolism disorders and facilitate the development of new therapeutic approaches." (PMID 38927431, 2024). "Conversely, among the top 10 proteins of HML pattern, four were related to lipid metabolism, including APOA1, KRT17, B2R8I2, and ATP8B3, demonstrating continuously increased lipid metabolism disorder with the increase of bacterial loads." (PMID 37908762, 2023). "Interestingly, the members of PPAR signaling pathway, APOA1 and PCK1 were often enriched in biological processes involved in lipid metabolism together with APOA4, and were related to lipid metabolic disorders." (PMID 38665091, 2024). "Bioinformatics analysis using IPA tools showed association of most altered proteins with mitochondrial dysfunction and lipid metabolism disorders and were clearly clustered with beta-2-adrenergic receptor (ADRB2), citrin (SLC25A13), and apolipoprotein A1 (APOA1)." (PMID 26030409, 2015).
liver cancer (10 papers, 2016 to 2024). An epithelial or non-epithelial malignant neoplasm that arises from the liver. "Low serum ApoA-1 levels were significantly associated with multiple tumors and high Barcelona Clinic Liver Cancer stage." (PMID 27683106, 2016). "Since CHB is a major risk for liver cancer, it may be one of the mechanisms of APOA1 downregulation in liver cancer." (PMID 36838613, 2023). "As demonstrated in this study, apolipoprotein A1, apolipoprotein B and HDL cholesterol were associated with oesophageal, gastric and liver cancers." (PMID 38263244, 2024). "The number of SNPs (nSNP) in the causal relationship between serum lipid indicators and liver cancer are as follows: 22 for LDL-c, 182 for ApoB, 9 for TG, 83 for TC, 92 for HDL-c, and 267 for ApoA1." (PMID 37746259, 2023). "Although the correlation of APOA1 with HCC has been confirmed by several studies, the mechanisms of APOA1 downregulation in liver cancer remain incompletely clear." (PMID 36838613, 2023).
multiple myeloma (10 papers, 2019 to 2025). "Research has shown that reduced levels of HDL cholesterol or apolipoprotein A1 correlate with elevated risks of multiple myeloma, MPN, non-Hodgkin lymphoma, and breast, lung, and nervous system cancers." (PMID 38972952, 2024). "Amyloid deposits in the lung and gastrointestinal tract were explored using MALDI-MSI, correlating peptide signatures with ApoE and ApoA1 in AL amyloidosis cases." (PMID 39595194, 2024). "Light chain (AL), reactive (AA), mutant or wild type transthyretin (ATTR), fibrinogen (AFib) and apolipoprotein A-I (ApoA1) are the most usual types of systemic amyloidosis, with AL amyloidosis being the most frequently diagnosed in developed world." (PMID 35348907, 2022). "The label free data also showed a couple of non-IgG related proteins that undergo dysregulation in multiple myeloma, among them being albumin and APOA1, aligning with established literature." (PMID 37835457, 2023).
Arthritis (9 papers, 2004 to 2025). Inflammation of a joint. "ApoB/ApoA1 ratio was positively correlated with the concomitant of arthritis (p=.019), hCRP (p=.036), diastolic blood pressure (p=.014), and weight (p=.001)." (PMID 34996506, 2022).
glaucoma (9 papers, 2020 to 2025). Increased pressure in the eyeball due to obstruction of the outflow of aqueous humor. "APOA1, on the other hand, had only discriminatory power to identify 76% of all glaucoma patients from healthy subjects." (PMID 34943212, 2021). "In particular, APOA1 and APOE have been shown to be elevated in the AH of primary open angle glaucoma patients as compared to patients with cataracts." (PMID 36362243, 2022). "Similar to our study, APOA1 and APOA2 levels were reportedly elevated in AH in patients with glaucoma shunt devices and corneal endothelial damage." (PMID 35401527, 2022). "This agrees with previous investigations wherein elevated levels of both APOA1 and APOC3 were detected among individuals with glaucoma." (PMID 34602085, 2021). "APOA1 and APOA4 were significantly 1.3 and 2.7 fold up-regulated in serum samples of glaucoma patients in comparison to controls." (PMID 34943212, 2021). "Within the African American cohort, APOA1, APOA2, APOA4, and APOD levels were significantly higher among glaucoma patients." (PMID 34602085, 2021). "In addition, upregulation of APOA1 and APLP2 in glaucoma samples was detected, as compared to ICL and cataracts." (PMID 39000104, 2024).
glioblastoma (9 papers, 2011 to 2025). The most malignant astrocytic tumor (WHO grade IV). "In vitro, the accumulation of cholesterol in bone marrow-derived macrophages decreased their phagocytic activity, and the restoration of cholesterol efflux with ApoA1 treatment increased their phagocytic activity against glioblastoma cells." (PMID 39196415, 2024). "The treatment of glioblastoma bearing mice with an engineered adenovirus expressing ApoA1 increased the phagocytic activity of TAM and decreased their PD-1 expression." (PMID 39196415, 2024). "Ectopic expression of the ABCA1/G1 ligand ApoA1 enhanced cholesterol efflux from TAM in the glioblastoma microenvironment and led to tumor clearance." (PMID 39196415, 2024). "In this study, we developed a recombinant APOA1-expressing adenovirus for targeted manipulation of cholesterol metabolism in glioblastoma therapy." (PMID 37474548, 2023). "CED of these recombinant cytokines in immunocompetent glioblastoma C57BL/6J mice nominated APOA1, IL-1B, and CCL4 as candidates that could increase immune cell infiltration and necrosis in the intracranial TIME." (PMID 40161763, 2025).
malaria (9 papers, 2010 to 2025). Malaria is a serious and sometimes fatal disease caused by a parasite that commonly infects a certain type of mosquito which feeds on humans. "This study provides valuable insights into the relationships between APOA1 gene polymorphisms, inflammatory markers, and parasite counts in Nigerian children with uncomplicated malaria." (PMID 40061813, 2025). "The role of genetic polymorphisms in modulating host responses to malaria has gained attention, with apolipoprotein A1 (APOA1) emerging as a candidate due to its anti-inflammatory and immunomodulatory properties." (PMID 40061813, 2025). "Investigating the functional effects of G-75A and C+83T polymorphisms on APOA1 expression and activity will provide deeper insights into their roles in malaria pathogenesis." (PMID 40061813, 2025). "Future research should focus on longitudinal studies to elucidate causal relationships between APOA1 polymorphisms, inflammatory biomarkers, and malaria outcomes." (PMID 40061813, 2025). "APOA1 levels are positively correlated with hemoglobin levels in malaria-infected primiparas, and low levels of APOA1 are associated with anemia, inflammatory deterioration, and poor prognosis in primiparous pregnant women during malaria infection." (PMID 33517144, 2021). "Given the dual role of APOA1 in lipid transport and inflammation, it is plausible that these polymorphisms might influence the inflammatory response in malaria." (PMID 40061813, 2025). "However, the cross-sectional design limits causal inferences between APOA1 polymorphisms, inflammatory biomarkers, and malaria outcomes." (PMID 40061813, 2025). "Finally, understanding genotype frequencies of APOA1 polymorphisms provides valuable insights for genetic studies in malaria-endemic regions." (PMID 40061813, 2025). "Additionally, exploring interactions between APOA1 polymorphisms and other factors, such as diet, co-infections, and prior malaria exposure, will help unravel the multifactorial determinants of inflammation in malaria." (PMID 40061813, 2025). "Significant differences were observed in the levels of inflammatory markers and APOA1 between the malaria and control groups." (PMID 40061813, 2025). "Second, the correlations between APOA1 and inflammatory markers highlight its potential as a biomarker and therapeutic target in malaria." (PMID 40061813, 2025). "Strong correlations between IL-6 and APOA1 levels in children with malaria suggest that APOA1 increases as the inflammatory response intensifies, potentially serving as a protective mechanism." (PMID 40061813, 2025). "The findings highlight the potential of IL-6, TNF-α, and APOA1 as biomarkers and therapeutic targets in malaria." (PMID 40061813, 2025). "The observed increase in APOA1 levels in malaria patients, despite the inflammatory state, suggests a compensatory mechanism to counteract oxidative and inflammatory stress." (PMID 40061813, 2025). "The key findings revealed major differences in the levels of inflammatory markers and APOA1 between children with malaria and healthy controls." (PMID 40061813, 2025). "This study underscores the potential role of APOA1 as a biomarker and therapeutic target in malaria, highlighting the influence of genetic and inflammatory factors on disease severity." (PMID 40061813, 2025). "APOA1 and inflammatory marker levels differed significantly between children with malaria and controls." (PMID 40061813, 2025). "Among the many proteins involved in the immune response to malaria, apolipoprotein A1 (APOA1) has been suspected to play a significant role." (PMID 40061813, 2025). "Altered correlations between inflammatory markers and APOA1 levels were also noted in children with malaria compared to controls." (PMID 40061813, 2025).
malaria (continued). "In children with malaria, the median APOA1 level was slightly higher at 74.0 mg/mL (IQR: 66.0 – 123.0), whereas the control group had a median level of 69.82 mg/mL (IQR: 58.37 – 78.2), with this difference also being statistically significant (p < 0.001)." (PMID 40061813, 2025). "In this study, APOA1 gene polymorphisms, serum levels of APOA1, and inflammatory markers (TNF-α and IL-6) were investigated in Nigerian children with uncomplicated malaria." (PMID 40061813, 2025). "A pilot descriptive prospective cross-sectional study to investigate the link between nutrition and immunity in Colombian children showed significantly lowered apolipoprotein A1 levels in the malaria group compared to the healthy controls." (PMID 24314058, 2013). "Children with malaria had decreased levels of apoA1 and albumin, but high levels of IL-10 when compared to children without malaria." (PMID 23208374, 2012). "Exploring how variations in the APOA1 gene affect these cytokine levels could help to understand malaria pathogenesis and identify potential biomarkers for disease severity." (PMID 40061813, 2025). "Given its anti-inflammatory properties, targeting APOA1 pathways could mitigate inflammatory damage in malaria patients." (PMID 40061813, 2025). "Beyond its primary functions, APOA1 has antioxidant, anti-inflammatory, and immunomodulatory properties, making it a protein of interest in the study of inflammatory diseases, including malaria." (PMID 40061813, 2025). "Finally, studies on APOA1 mimetics or other anti-inflammatory interventions could pave the way for novel therapeutic strategies to improve malaria outcomes." (PMID 40061813, 2025). "In contrast, the correlation between TNF-α and APOA1 levels in the uncomplicated malaria group was not statistically significant (Spearman rho r = 0.098, p = 0.495)." (PMID 40061813, 2025).
migraine (9 papers, 2021 to 2026). "In a large cohort, a significant association was found between altered lipid metabolism and migraine: in migraineurs, apolipoprotein A1, high-density lipoprotein and free cholesterol were decreased." (PMID 40340645, 2025). "ApoA1 levels were significantly associated with migraine in male participants, with smaller effects, but in similar direction, in female participants." (PMID 37277733, 2023). "Plasma metabolomics in migraine patients indicate decreased levels of apolipoprotein A1, reduced ratios of free cholesteryl esters to total lipids in small HDL subtypes, and significantly decreased omega-3 fatty acids in men only." (PMID 39850553, 2024). "The expanded model revealed that a decreased apoA1 level and S-HDL-FC ratio were still associated with migraine." (PMID 37277733, 2023). "Sex-specific findings showed a less CVD-protective HDL metabolism as well as the ApoA1 lipoprotein, especially for women with migraine." (PMID 37277733, 2023). "This study identified two circulating candidate migraine biomarkers, which are both related to HDL status: a decreased level of apoA1 (an apolipoprotein with a specific association with HDL) and a decreased S-HDL-FC ratio (the free cholesterol to total lipid ratio in small HDL)." (PMID 37277733, 2023). "In summary, this large 1H-NMR-based metabolomics study showed a sex-specific decrease in apoA1, with especially lower values in males with migraine but not in women." (PMID 37277733, 2023). "Finally, two proteins were down-regulated in both groups of patients with migraine vs CTRL, including apolipoprotein A-I (APOA1) and alpha-1-antitrypsin (A1AT), while two protein spots, identified as transthyretin (TTHY) and pepsin A-3 (PEPA3), were up-regulated in the same comparison." (PMID 33923220, 2021). "Another very small study analyzed in menstrual-related migraine (n = 15), menopausal migraine (n = 15) and non-headache (n= 15) women the serum profile, wherein apoA1 was found to be decreased in the migraine women, but no robust data could be presented because of the small sample size." (PMID 37277733, 2023).